SLC2A9 (solute carrier family 2 member 9)
Diseases named in the same sentence as SLC2A9 in open-access papers (continued):
Sharing a sentence is not in itself a finding about the gene and the disease.
gout (continued). "Research has identified various single nucleotide polymorphisms (SNPs) in the SLC2A9 and SLC22A12 gene that are associated with an increased risk of hyperuricaemia and gout, such as G/A genotype for rs3733591 in the SLC2A9 gene and a C/C genotype for rs893006 in the SLC22A12 gene." (PMID 40093021, 2025). "Pacific Islander, Māori, and African American populations demonstrate both elevated baseline hyperuricemia and greater obesity-attributable gout risk compared to white populations, likely reflecting genetic variants in urate transporters (ABCG2, SLC2A9) interacting with metabolic factors." (PMID 41227037, 2025). "In summary, metabolic syndrome and SLC2A9 rs3733591 genotypes were interactively associated with gout in Taiwanese men, but not women." (PMID 38689651, 2024). "This is an iSNP located in the intron (DNA segment that does not contain genetic information or code for proteins) of SLC2A9, which also contains rs11936395 found in this study, and is associated with increased serum urate levels and risk of gout." (PMID 38060535, 2023). "Nevertheless, the results of the current study imply that genotyping for polymorphism at the SLC2A9 and ABCG2 genes may be useful when counselling gout patients about risk of hypertension and the need to take preventative measures." (PMID 35633389, 2022). "Adherence to dietary recommendations, BMI (< 25 kg/m2), and absence of the SLC2A9 rs12498742 urate-raising allele produced PAFs for HU of 20 to 24%, 59 to 69%, and 57 to 64%, respectively, in the three non-gout cohorts." (PMID 33663556, 2021). "Therefore, an updated systematic review and meta-analysis regarding the influence of SNPs in ABCG2 and SLC2A9 on gout, hyperuricemia and serum urate is needed." (PMID 33087043, 2020). "However, we are the first to report both pooled homozygous and heterozygous effects of these SLC2A9 SNPs on gout." (PMID 33087043, 2020). "Interestingly, variants p.A17T (OR (odds ratio) = 3.44, p = 0.0023, p-value adjusted = 0.0432) and c.-40-13T>C (OR = 3.18, p = 0.0306, p-value adjusted = 0.2510) of SLC2A9 were observed to be more frequent in patients with gout." (PMID 32759716, 2020). "Unlike these reports, our study shows that the SLC2A9 variant exerts a greater risk of gout compared with the ABCG2 variant." (PMID 30626429, 2019). "In contrast, other serum urate-associated variants, including SLC2A9, do not demonstrate gene-sex interactions for gout risk." (PMID 30626429, 2019). "844G > A) in the SLC2A9 gene had significant effects on gout in an Asian population." (PMID 30189835, 2018). "Genome-wide significant associations with serum urate and gout were identified for known loci at SLC2A9 and ABCG2, but not for novel loci." (PMID 30181573, 2018). "In addition, five genes (PKD2, SLC2A9, SLC17A1, SLC17A4 and SLC17A2) were determined to influence the risk of gout (all PFDR < 0.05)." (PMID 29497127, 2018). "Some variation in gout prevalence may be specifically attributable to genetic factors, such as variation in renal urate transporter genes, particularly SLC2A9 and ABCG2." (PMID 29996922, 2018). "Similarly, evidence has been demonstrated for interaction of sugar-sweetened beverage consumption with a urate-associated variant of SLC2A9 and alcohol intake with LRP2 in determining the risk of gout and the risk of HU and gout, respectively." (PMID 28679452, 2017). "It is known that SLC2A9 encodes the GLUT9 transporter, a renal uric acid transporter, and genetic variants of the transporter associate with blood levels of uric acid and risk of gout." (PMID 29375475, 2017). "Finally, a non-additive interaction between diuretic use and genotype at each of SLC2A9 and SLC22A11 in the risk of gout in hypertensive people has been reported in the Atherosclerosis Risk in Communities study." (PMID 25889045, 2015).
gout (continued). "Therefore, we performed a genetic association study of these SUA loci (PDZK1, GCKR, SLC2A9, LRRC16A, SLC17A1, SLC16A9, SLC22A11 and SLC22A12) in gout patients and normal control volunteers of Han Chinese origin." (PMID 26290326, 2015). "Previous studies identified several transporter genes associated with gout, such as ATP-binding cassette transporter, subfamily G, member 2 (ABCG2/BCRP), GLUT9/SLC2A9, monocarboxylate transporter 9 (MCT9/SLC16A9), and organic anion transporter 4 (OAT4/SLC22A11)." (PMID 24318514, 2014). "Recent genome-wide association studies (GWAS) consistently showed that the minor alleles of several single nucleotide polymorphisms (SNPs) in the solute carrier family 2 member 9 gene (SLC2A9 ) were associated with lower plasma urate concentration and predicted lower gout risk." (PMID 23422251, 2013). "Genomewide association studies in Caucasian cohorts have shown that intronic variants (rs7442295 and surrogate marker rs11942223) within the solute carrier family 2, member 9/facilitated glucose transporter 9 (SLC2A9/GLUT9) gene are associated with high serum urate concentrations and gout." (PMID 21658257, 2011). "However, as previously reported, rs6855911 in SLC2A9 gene showed deviation from HWE in gout cases (p = 0.01)." (PMID 19890391, 2009). "SNP markers in SLC2A9 and ABCG2 genes were found to be strongly associated with the phenotype gout." (PMID 19890391, 2009). "The first demonstrated that human SLC2A9 is a high capacity, low affinity uric acid transporter and that genetic variants are associated with gout; however causative mutations were not determined." (PMID 18989453, 2008). "Gene SLC2A9 is the major independent gene of controlling uric acid and governing gout attack in those carrying rs2231142 wild-type; and PRS provides a robust insight into the genetic component of gout and AH in the selection of variant-effect types on the traits." (PMID 36221101, 2022). "Recent GWAS identified genetic variants in urate transporters (ABCG2, SLC2A9, SLC22A11) and metabolic genes (GCKR, ADH1B) to be associated with the transition from hyperuricaemia to gout, and several of these associated with serum urate (SU) and gout in previous studies." (PMID 35633389, 2022). "Meta-analysis showed that SNP rs16890979, rs1014290and rs12510549 of SLC2A9 could prevent gout." (PMID 35922835, 2022). "Therefore, SLC2A9 SNPs may have a protective effect on gout, but its severe hypouricemia and its complications may endanger the lives of patients." (PMID 35922835, 2022). "For SLC2A9 polymorphisms, mainly studied in Caucasians, carrying 1–2 minor alleles of rs1014290, rs6449213, rs6855911, and rs7442295 were about 25–43%, 31–62%, 33–64%, and 35–65% significantly lower odds of gout than non-minor-allele-genotypes." (PMID 33087043, 2020). "This may be because a high proportion (> 90%) of participants in the analysis had at least one SLC2A9 effect allele and, in particular, there were very few women with gout who did not carry an effect allele (n = 8)." (PMID 30626429, 2019). "However, we did not observe differential sex-specific differences for SLC2A9 on gout risk in the interaction analysis." (PMID 30626429, 2019). "Meta-analysis of 14 prior studies totaling 28,141 participants demonstrated that genetic polymorphisms of SLC2A9 and URAT1 are key regulators of urate homeostasis, as the inheritance of one predisposing variant of SLC2A9 or URAT1 significantly increases the risk for an individual to develop gout." (PMID 29214547, 2018). "The aim of this study was to determine whether the non-synonymous variants rs2280205 and rs2276961 of the SLC2A9 gene in Cameroonians have no influence on urinary excretion of uric acid and the risk of developing gout as seen in the Caucasian population." (PMID 29615104, 2018).
gout (continued). "We have previously reported that a non-synonymous SLC2A9 Arg265His variant is associated with tophi in New Zealand Māori with gout, and a Taiwanese study has reported an association between ABCG2 Q141K and tophi in both Han Chinese and Taiwanese aboriginal people with gout." (PMID 28270222, 2017). "All the urate transporter-coding genes, ABCG2, SLC2A9, SLC17A1 and SLC17A4, showed association with both the serum urate concentration and progression from hyperuricemia to gout and could affect the risk of gout." (PMID 28252667, 2017). "This might be explained if the SLC2A9 gene is the common pathway that links gout with metabolic syndrome and these other phenotypic disease characteristics in our study, such as serum triglycerides levels, BMI values, diastolic blood pressure, and systolic pressure levels." (PMID 22393348, 2012). "Overall, the SLC family, particularly SLC22A12 and SLC2A9 along with ABCG2, play important roles in UA transportation, and their dysfunction can contribute to hyperuricemia and gout." (PMID 38674582, 2024). "While fructose consumption patterns could partly explain the global rise in gout prevalence, it was also reported that fructose-induced hyperuricemia is not equally distributed across different populations, due to genetic polymorphisms in the GLUT-9 encoding gene (SLC2A9)." (PMID 36079846, 2022). "In a cohort of 250 individuals with primary hyperuricemia and gout, we used direct sequencing to examine the SLC22A12 and SLC2A9 genes." (PMID 32759716, 2020). "For example, urate transporter genes ABCG2, SLC2A9, and SLC22A12 modulate the relationship of renal urate homeostasis and gout with T2DM." (PMID 30615649, 2019). "SLC2A9 and ABCG2 are the two most prominent players in gout explaining ~5% of variance in serum urate levels." (PMID 30181573, 2018). "None of the variants of the known gout and hyperuricemia-related genes were co-segregated with the disease phenotype in this family, including ABCG2, SLC2A9, SLC22A11, SLC22A12, SLC17A1, SLC17A3, PDZK1, and INHBB." (PMID 39433541, 2024). "Previous studies have found that the gut of gout patients is rich in the bacterial metabolites acetate, succinate, and glucose, which provide energy for the intestinal epithelium to excrete UA through the transporter ABCG2 and SLC2A9." (PMID 38674582, 2024). "According to a GWAS analysis in Han Chinese and Solomon Islanders, SNPs rs3733591, rs3733589, and rs1014290 in SLC2A9 affect gout in Han Chinese but not in Solomon Islanders." (PMID 38060535, 2023). "In addition, a recent GWAS found that ABCG2, SLC2A9, ALDH2, and novel loci induce asymptomatic hyperuricemia into gout development." (PMID 33087043, 2020). "The observation that adjustment for allopurinol intake was important in detecting genetic effects on gout in this study implies that allopurinol is a well working drug regardless of the observed SLC2A9 and ABCG2 genotype." (PMID 30181573, 2018). "There is evidence that SLC2A9 (rs13129697) and SLC22A11 (rs2078267) genotype interact with diuretics to determine the risk of gout, although this was not replicated in a larger study." (PMID 26528330, 2015). "Additionally, we found only weak epistatic interaction between SNPs in SLC2A9 and LRRC16A on gout, making a relevant additive effect of SNPs influencing serum UA levels on the qualitative trait unlikely." (PMID 19890391, 2009). "The pathogenic variants of SLC2A9 were assessed in all participants, and the frequency of rs3733591, which has been reported to be related to SUA, was not significantly different between the gout and asymptomatic hyperuricemia groups." (PMID 38397902, 2024). "The PAFs for BMI and SLC2A9 rs12498742 were lower than for the non-gout cohorts (57 to 69% in non-gout and 48 to 49% in gout), and non-adherence to the Healthy Eating Pyramid guidelines was 21.4% in non-gout (cohort 3) and 11.8% in gout." (PMID 33663556, 2021).
gout (continued). "This hypothesis is further supported by the observation that the effect size of ABCG2 on urate in Europeans and Japanese is 58% and 73% that of SLC2A9, the most influential urate locus, respectively, yet the effect size of ABCG2 on gout is consistently larger than that of SLC2A9." (PMID 32164793, 2020). "Six genes (A1CF, ABCG2, SLC2A9, TRIM46, SLC17A1 and SLC17A4) exhibited effects on the development of gout from hyperuricemia in males (all P < 0.05), but none of them exhibited such effects in females (all P > 0.05)." (PMID 28252667, 2017).
hyperuricemia (92 papers, 2008 to 2026). An abnormally high level of uric acid. "Variants or abnormal expression of SLC2A9 significantly alter serum uric acid levels, playing a pivotal role in the pathogenesis of hyperuricemia." (PMID 41601955, 2026). "A total of 194 Tibetan patients with hyperuricemia and 304 healthy Tibetan controls were enrolled, and polymorphisms in SLC2A9 (rs1014290), SLC22A12 (rs559946), and SLC22A11 (rs1783811) were identified using high-resolution melting." (PMID 41137353, 2025). "GLUT9, encoded by the SLC2A9 gene, is an important proximal tubular transporter protein for UA and plays a key role in hyperuricemia." (PMID 35656068, 2022). "It was also recently reported that the association of ABCG2 rs2231142 with hyperuricemia is modified by SLC2A9 polymorphism in an elderly Chinese population." (PMID 33531973, 2021). "SLC2A9, which is mainly expressed in the liver, kidney, and intestine (jejunum), is the most common cause of hyperuricemia." (PMID 30239845, 2019). "The aim of this study was to explore the associations of haplotypes of the glucose transporter 9 (SLC2A9) genes with type 2 diabetes mellitus (T2DM) complicated with hyperuricemia (HUA)." (PMID 30087870, 2018). "GLUT9 (encoded by the SLC2A9 gene) was found to be a new target for the treatment of hyperuricemia as a high-capacity urate transporter." (PMID 28623927, 2017). "By knocking out the uric acid transporter SLC2A9 in mice, DeBosch and colleagues found that hyperuricemia causes several phenotypes of the metabolic syndrome, including obesity, dyslipidemia and hypertension." (PMID 27886242, 2016). "Given the heterogeneity evident in risk conferred for hyperuricemia at SLC2A9 and SLC22A12 in different populations studied so far, further investigation of these genes is warranted." (PMID 25268603, 2014). "Notably, mice exhibiting hyperuricemia accompanied by early onset nephropathy, which is like acute hyperuricemia nephropathy in humans, have been produced by complete knockout of the SLC2A9 gene, which encodes GLUT9." (PMID 39770922, 2024). "Moreover, the variants of SLC2A9 show protective and opposing effects on hyperuricemia in those carrying the rs2231142 wild genotype." (PMID 36221101, 2022). "The development of hyperuricemia has been shown to be associated with multiple genetic factors and the uric acid transporter protein genes SLC2A9 (encoding GLUT9), SLC22A12 (encoding URAT1), SLC17A1 (encoding NPT1) and ABCG2 were most strongly correlated with changes in serum uric acid levels." (PMID 35909538, 2022). "The SLC2A9 gene may modulate the association between hyperuricemia and diabetes and have a higher effect on SUA levels in women than in men, which possibly suggests a genetic basis for the sex differences." (PMID 32775463, 2020). "A small Mendelian randomization study supports the hypothesis that hyperuricemia, driven by an instrumental variant in SLC2A9, is causal in chronic kidney disease progression." (PMID 29904633, 2018). "On one hand SLC2A9 mutations are associated with hypouricemia and hyperuricosuria, while on the other, mutations in SLC2A9 that alter the protein impair urate secretion into the urine resulting in hyperuricemia." (PMID 24379826, 2013). "GWAS studies of hyperuricemia have identified key susceptibility loci involved in uric acid transport and purine metabolism: Primary transporters include GLUT9 (SLC2A9) and URAT1 (SLC22A12), which mediate uric acid reabsorption." (PMID 41601955, 2026). "Association between SLC2A9, SLC22A12 and SLC22A11 polymorphisms and the risk of higher SUA values in hyperuricemia group." (PMID 41137353, 2025). "In this case-control study, we investigated for the first time the association between rs1014290 (SLC2A9), rs559946 (SLC22A12), and rs1783811 (SLC22A11) with SUA levels and hyperuricemia in a Tibetan population." (PMID 41137353, 2025).
hyperuricemia (continued). "Genetic polymorphisms in genes encoding urate transporters, such as SLC2A9 (GLUT9) and ABCG2, have been associated with altered renal urate excretion and an increased risk of hyperuricemia and gout." (PMID 39409183, 2024). "SLC2A9, another significant uric acid transporter in the kidney, is crucial for uric acid excretion, hyperuricemia treatment, and uric acid reabsorption." (PMID 38257077, 2024). "In conclusion, this study confirms the association between the SLC2A9 and ABCG2 genes and hyperuricemia." (PMID 31207883, 2019). "In SLC2A9 knockout mice, the animals exhibited a complex metabolic syndrome of hyperuricemia, hyperuricosuria, spontaneous hypertension, and dyslipidemia." (PMID 30239845, 2019). "Another transporter, SLC2A9, is also important in intestinal secretion, and knockdown of intestinal SLC2A9 can also result in hyperuricemia and features of metabolic syndrome." (PMID 30142173, 2018). "In mice a hepatocyte-specific SLC2A9 knockout develops severe hyperuricemia, consistent with a role for SLC2A9 in hepatic uptake of uric acid." (PMID 25889045, 2015). "In mice, live specific knockout of SLC2A9 results in hyperuricemia and hyperuricosuria due to decreased degradation of UA by hepatic uricase." (PMID 26167684, 2015). "The Dalmatian dog model of hyperuricosuria and hyperuricemia underscores the importance of SLC2A9 for uric acid transport in mammals." (PMID 18989453, 2008). "Associations between SLC2A9, SLC22A12 and SLC22A11 SNPs and hyperuricemia." (PMID 41137353, 2025). "Bergenin, a C-glucoside of 4-O-methyl gallic acid isolated from several medicinal plants, has been shown to reduce serum urate levels in a hyperuricemia-induced mouse model by elevating Abcg2 expression in both the kidney and intestine and by suppressing Slc2a9 expression in the kidney." (PMID 36483739, 2022). "Indeed, urate transporter genes such as SLC22A12 (also known as URAT1), SLC2A9 (GLUT9), and ABCG2 (BCRP) have been markedly associated with SUA, hyperuricemia, and gout." (PMID 30993211, 2019). "Additionally, under the additive model, we observed statistically significant associations between hyperuricemia and the ABCG2 SNPs and SLC2A9 genes." (PMID 31207883, 2019). "However, in the present study we identified two previously reported loci (SLC2A9 and ABCG2) associated with the serum levels of UA and hyperuricemia." (PMID 31207883, 2019). "Interestingly, mice with a gut-specific SLC2A9 knockout developed a metabolic syndrome-like condition in addition to hyperuricemia." (PMID 25889045, 2015). "Probiotics and prebiotics have been shown to ameliorate hyperuricemia in mice by modulating the gut microbiota and increasing the expression of UA exporter genes such as ABCG2 and SLC2A9." (PMID 38674582, 2024). "For hyperuricemia, two very recent GWA studies in an isolated Sardinian population and in a British cohort identified SNPs in the GLUT9 gene, also known as SLC2A9, to significantly influence serum UA levels." (PMID 18398472, 2008). "Depletion of the Slc2a9 gene specifically in the liver results in severe hyperuricemia and hyperuricosuria, in the absence of urate nephropathy or any structural abnormality of the kidney as were found in the whole-body knockout model." (PMID 32591906, 2020). "Furthermore, including SLC2A9 rs13113918 genotype in logistic regression models improved the prediction of prevalent hyperuricemia at all three time points compared to models not including genotype." (PMID 23272134, 2012).